NUDT21 (nudix hydrolase 21)
Description:
Component of the cleavage factor Im (CFIm) complex that functions as an activator of the pre-mRNA 3'-end cleavage and polyadenylation processing required for the maturation of pre-mRNA into functional mRNAs. CFIm contributes to the recruitment of multiprotein complexes on specific sequences on the pre-mRNA 3'-end, so called cleavage and polyadenylation signals (pA signals). Most pre-mRNAs contain multiple pA signals, resulting in alternative cleavage and polyadenylation (APA) producing mRNAs with variable 3'-end formation. The CFIm complex acts as a key regulator of cleavage and polyadenylation site choice during APA through its binding to 5'-UGUA-3' elements localized in the 3'-untranslated region (UTR) for a huge number of pre-mRNAs. NUDT21/CPSF5 activates indirectly the mRNA 3'-processing machinery by recruiting CPSF6 and/or CPSF7. Binds to 5'-UGUA-3' elements localized upstream of pA signals that act as enhancers of pre-mRNA 3'-end processing. The homodimer mediates simultaneous sequence-specific recognition of two 5'-UGUA-3' elements within the pre-mRNA. Plays a role in somatic cell fate transitions and pluripotency by regulating widespread changes in gene expression through an APA-dependent function (By similarity). Binds to chromatin (By similarity). Binds to, but does not hydrolyze mono- and di-adenosine nucleotides.
Synonyms: CFIm25; CPSF5
Tractability: Small molecule: a structure with a bound ligand is known; it has a high-quality binding pocket. PROTAC: ubiquitination databases record sites on it; its protein half-life has been measured.
Gene: Protein-coding gene on chromosome 16 (56,429,133 to 56,452,199, reverse strand). Ensembl gene ENSG00000167005.
Subcellular location: Nucleus; Cytoplasm
Subcellular location (Human Protein Atlas): Nuclear bodies; Centriolar satellite
Pathways (Reactome):
Metabolism of RNA: Processing of Intronless Pre-mRNAs; mRNA 3'-end processing; mRNA Polyadenylation
Disease: Dengue Virus-Host Interactions
Gene expression (Transcription): RNA Polymerase II Transcription Termination
Gene Ontology:
Molecular function: histone deacetylase binding; identical protein binding; mRNA 3'-UTR AU-rich region binding; mRNA binding; protein binding; protein homodimerization activity; RNA binding; chromatin binding
Biological process: co-transcriptional mRNA 3'-end processing, cleavage and polyadenylation pathway; mRNA 3'-end processing; mRNA alternative polyadenylation; mRNA processing; protein heterotetramerization; protein tetramerization; positive regulation of pro-B cell differentiation; positive regulation of stem cell differentiation; post-transcriptional regulation of gene expression
Cellular component: centrosome; cytoplasm; mRNA cleavage and polyadenylation specificity factor complex; mRNA cleavage factor complex; nuclear body; nucleus; paraspeckles; nucleoplasm
Genetic constraint (gnomAD): Loss-of-function variants: 2 observed, 12.24 expected, observed/expected ratio (o/e) 0.16, 90% interval 0.066 to 0.51. The upper end of that interval is the gene's LOEUF score, 0.51, which puts it in group 2 of 6, group 1 being the genes least tolerant of losing a copy. Missense variants: 36 observed, 171.04 expected, observed/expected ratio (o/e) 0.21, 90% interval 0.16 to 0.28. Synonymous variants: 81 observed, 66.89 expected, observed/expected ratio (o/e) 1.21, 90% interval 1.01 to 1.46.
Homologues: Orthologues: chimpanzee NUDT21 (100% identical), macaque NUDT21 (100% identical), dog NUDT21 (99% identical), mouse Nudt21 (99% identical), rabbit NUDT21 (99% identical), rat Nudt21 (99% identical), guinea pig NUDT21 (98% identical), zebrafish nudt21 (98% identical), tropical clawed frog nudt21 (96% identical), Drosophila melanogaster Cpsf5 (79% identical), Caenorhabditis elegans cfim-1 (63% identical).
Diseases named in the same sentence as NUDT21 in open-access papers:
NUDT21 is named in the same sentence as 69 diseases in open-access papers, as found by Europe PMC text mining. Sharing a sentence is not in itself a finding about the gene and the disease. The quoted sentences say what the papers report.
glioblastoma (18 papers, 2015 to 2024). The most malignant astrocytic tumor (WHO grade IV). "Research found that depletion of NUDT21 not only causes increased pPAS usage but also increases cell proliferation and enhances glioblastoma(GBM) cell tumorigenicity." (PMID 36816917, 2023). "In glioblastoma patients, NUDT21 expression is reduced, with lower levels being associated with shortened 3′UTRs and worse survival." (PMID 32560344, 2020). "Current studies have demonstrated that NUDT21 regulates bladder cancer, hepatocellular carcinoma, glioblastoma, leukemia, breast cancer, and gastric cancer." (PMID 38349866, 2024). "Supporting a role in 3′UTR shortening, depletion of NUDT21 in glioblastoma cells results in proximal PAS usage as well as increased cell proliferation and tumorigenicity." (PMID 32560344, 2020). "Our results are supported by Lou and colleagues, who demonstrated NUDT21 is an upstream regulator of the NF-κB pathway which controls the mesenchymal identity of glioblastoma cells." (PMID 31695759, 2019). "Knockdown of NUDT21 in glioblastoma cells results in shortened 3′-UTRs in 1450 transcripts and an increase in cell proliferation." (PMID 27144453, 2016). "A total of 59 genes have increased proximal p(A) site usage when comparing low- to high-NUDT21 expressing glioblastoma tumors, and of these, 24 show the same effect as that following CFIm25 knockdown in HeLa cells." (PMID 26312503, 2015). "To gain insights into the cause-and-effect relationship from 3′US-mediated HK gene repression to tumorigenesis, we revisited a previous study in which 3′US-ceRNA effect promotes tumorigenesis in NUDT21 knockdown (KD) in HeLa cells and glioblastoma [data available in GSE42420 and GSE78198]." (PMID 32411683, 2020). "However, a comparison between the transcripts affected after NUDT21 knockdown in glioblastoma cells and those up- and down-regulated in NuKO cells revealed no overlap between the down-regulated genes and only 1 overlap in the top 250 up-regulated genes." (PMID 27144453, 2016). "Lou demonstrated that the NF-kB inhibitor zeta (NFKBIZ) was a downstream target of NUDT21, and that MES recognition genes CHI3L1 and FN1 were differentially regulated in glioblastoma cells." (PMID 38349866, 2024). "It was reported that the knockdown of one of the CPSF complex members, NUDT21 (also called CPSF5), led to 3’US of oncogenes and increased glioblastoma cell proliferation." (PMID 38503731, 2024).
hepatocellular carcinoma (14 papers, 2018 to 2024). A malignant tumor that arises from hepatocytes. "The bubble map showed that NUDT21 was associated with diseases such as chronic lymphatic leukemia and hepatocellular carcinoma." (PMID 38349866, 2024). "NUDT21 levels are also reduced in hepatocellular carcinoma and bladder cancer, and low NUDT21 associates with shorter 3′UTRs and adverse outcome." (PMID 32560344, 2020). "The decreased expression of NUDT21 was also found in cancers, such as hepatocellular carcinoma, breast cancer, and bladder cancer." (PMID 37077345, 2023). "Other studies have also found that NUDT21 is down-regulated in hepatocellular carcinomas (HCCs), where NUDT21 is involved in 3’UTR lengthening." (PMID 33526057, 2021). "In contrast, we reported that the expression of NUDT21 is repressed, which contributes to hepatocellular carcinoma suppression." (PMID 33648552, 2021). "Interestingly, circBARD1 and circMAN1A2, which showed the highest downregulation under NUDT21-knockdown conditions, were also regulated by NUDT21 in hepatocellular carcinoma cells." (PMID 38338754, 2024). "However, in our previous study, we have found NUDT21 inhibits cell proliferation and metastasis in human hepatocellular carcinoma and breast cancer." (PMID 34660260, 2021). "NUDT21 regulates circRNA cyclization and ceRNA crosstalk in hepatocellular carcinoma." (PMID 32493490, 2020). "However, NUDT21 was identified to be a tumor suppressor in human cervical cancer, bladder cancer, lung cancer (including small cell lung cancer and non-small cell lung cancer), breast cancer, and hepatocellular carcinoma." (PMID 34660260, 2021). "In hepatocellular carcinoma (HCC), the expression level of circRNA is generally down-regulated, and the level of NUDT21 is also significantly down-regulated, HCC patients with low levels of NUDT21 have poor overall survival." (PMID 34439339, 2021).
bladder cancer (9 papers, 2019 to 2024). "Although the tumor‐suppressor function of NUDT21 has been reported in bladder cancer, breast cancer, and lung cancer, its involvement in melanoma has not been reported preclinically and clinically." (PMID 37356089, 2023). "We then assessed NUDT21 expression in 10 bladder cancer tissue specimens and cell lines with qRT-PCR and WB." (PMID 31695759, 2019). "The present study for the first time revealed NUDT21 not only attenuates Wnt/β-catenin signaling, but also inactivates NF-KB signaling in bladder cancer cells." (PMID 31695759, 2019). "In vitro and in vivo assays were performed to investigate the function of NUDT21 in tumorigenesis in bladder cancer cells." (PMID 31695759, 2019). "NUDT21 inhibits bladder cancer progression by regulation of APA-mediated 3'UTR alterations." (PMID 32929364, 2020). "In addition, NUDT21 was significantly down-regulated in all 9 bladder cancer cell lines as compared with NBUCs and normal urothelial cells." (PMID 31695759, 2019). "At present, studies have shown that NUDT21 is involved in the occurrence and development of many kinds of tumors, including glioblcomplementarily astoma, cervical cancer, breast cancer, bladder cancer, pancreatic ductal adenocarcinoma, small cell lung cancer, gastric tumorigenesis." (PMID 36816917, 2023). "In addition, as our previous study showed that NUDT21 inhibits bladder cancer growth and metastasis via suppressing the expression of Wnt signaling targets, we compared the genes whose APA is regulated by PABPN1 in the present study and those by NUDT21, and found few overlap target genes." (PMID 36879298, 2023). "The research in 2019 for the first time provide novel insight into the crucial role played by NUDT21 in regulation of APA-mediated 3′-UTR alterations, which further promote bladder cancer (BC) progression." (PMID 36816917, 2023). "However, neither the role NUDT21 plays in bladder cancer (BC) nor the mechanisms which are involved have been investigated." (PMID 31695759, 2019).
breast cancer (7 papers, 2020 to 2023). A primary or metastatic malignant neoplasm involving the breast. "Low expression of NUDT21 is associated with tumor size, stage, and metastasis correlating with poor overall and recurrence-free survival in breast cancer patients, and overexpression of NUDT21 inhibits invasion, EMT, and proliferation in cell culture." (PMID 33668737, 2021).
gastric cancer (7 papers, 2018 to 2024). A primary or metastatic malignant neoplasm involving the stomach. "High level of NUDT21 was associated with poor overall survival (OS) rates in gastric cancer patients." (PMID 34660260, 2021). "Therefore, high level of NUDT21 was associated with poor clinicopathological features and survival rates in gastric cancer patients." (PMID 34660260, 2021). "Association of NUDT21 expression with clinicopathological features in gastric cancer patients." (PMID 34660260, 2021). "NUDT21 could be used as a potential diagnostic and therapeutic target for human gastric cancer." (PMID 34660260, 2021). "They found that NUDT21 expression was positively correlated with tumor size, lymph node metastasis and clinical stage in gastric cancer patients." (PMID 36816917, 2023). "For further study, the mRNA levels of NUDT21 in the 70 gastric cancer tissues and 70 normal gastric tissues were also examined." (PMID 34660260, 2021). "NUDT21 expression was positively correlated with tumor size, lymph node metastasis and clinical stage in gastric cancer patients." (PMID 34660260, 2021). "High level of NUDT21 was correlated with poor clinicopathological features and survival rates in gastric cancer patients." (PMID 34660260, 2021). "In this study, we reported that NUDT21 promoted cell proliferation, colony formation, cell migration and invasion in gastric cancer cells." (PMID 34660260, 2021). "We herein reported that SGPP2 was specifically regulated by NUDT21, promoting gastric cancer cell proliferation and metastasis, and mediated the oncogenic role of NUDT21 in gastric cancer cells." (PMID 34660260, 2021). "Through high throughput RNA-sequencing, an important oncogene SGPP2 (sphingosine-1-phosphate phosphatase 2, also known as SPP2) was found to be positively regulated by NUDT21 and mediated the tumor promoting role of NUDT21 in gastric cancer cells." (PMID 34660260, 2021). "The mRNA levels of NUDT21 were extremely higher in gastric cancer cells compared with normal gastric cells (P<0.05)." (PMID 34660260, 2021). "SGPP2 was positively regulated by NUDT21 and mediated the oncogenic role of NUDT21 in gastric cancer cells." (PMID 34660260, 2021). "Among the five gastric cancer cell lines, the basal level of NUDT21 was highest in BGC-823 cells, and was lowest in MKN-28 cells." (PMID 34660260, 2021). "For downstream mechanisms, SGPP2 was identified to be positively regulated by NUDT21 in gastric cancer cells." (PMID 34660260, 2021). "The expression levels of NUDT21 were also much higher in gastric cancer tissues from patients with distant metastasis compared with those of patients without distant metastasis." (PMID 34660260, 2021). "Through high throughput RNA-sequencing, SGPP2 was identified to be positively regulated by NUDT21 and mediated the tumor promoting role of NUDT21 in gastric cancer cells." (PMID 34660260, 2021). "To explore the downstream mechanisms involved in the tumor promoting role of NUDT21 in gastric cancer cells, we performed high throughput RNA-sequencing to find gene differential expression between BGC-823-sh-NUDT21#1 and BGC-823-sh-ctrl cells." (PMID 34660260, 2021). "The expression levels of NUDT21 were much higher in human gastric cancer tissues/cells compared with normal gastric tissues/cells." (PMID 34660260, 2021). "Forced expression of NUDT21 concordantly promoted both cell proliferation and metastasis in gastric cancer cells." (PMID 34660260, 2021). "Concordantly, the mRNA levels of NUDT21 were significantly higher in the gastric cancer tissues compared with normal gastric tissues." (PMID 34660260, 2021). "The expression levels of NUDT21 were found to be much higher in human gastric cancer tissues compared with normal gastric tissues." (PMID 34660260, 2021). "Gastric cancer cell lines BGC-823 and MKN-28 were selected to examine the functional role of NUDT21 in gastric cancer cells." (PMID 34660260, 2021).
gastric cancer (continued). "High expression level of NUDT21 was associated with tumor size, lymph node metastasis and clinical stage in gastric cancer patients, and patients with high expression of NUDT21 showed poor OS rates compared with patients with low expression of NUDT21." (PMID 34660260, 2021). "NUDT21 protein was mainly located in the cytoplasm of gastric cancer cells and glandular epithelial cells." (PMID 34660260, 2021). "In this study, we demonstrated that NUDT21 was high expressed in human gastric cancer tissues/cells compared with normal gastric tissues/cells." (PMID 34660260, 2021). "The expression levels of NUDT21 were extremely higher in gastric cancer tissues (64.3%) compared with normal gastric tissues (40.0%) (P<0.01)." (PMID 34660260, 2021). "In this study, we systematically examined the functional role of NUDT21 in human gastric cancer cells." (PMID 34660260, 2021). "Gastric cancer patients with high expression of NUDT21 showed poor clinicopathological parameters and overall survival (OS) rates." (PMID 34660260, 2021). "The expression levels of NUDT21 were also higher in gastric cancer tissues from patients with distant metastasis compared with the tissues from patients without distant metastasis." (PMID 34660260, 2021). "Forced expression of NUDT21 enhanced cell oncogenic futures of gastric cancer cells." (PMID 34660260, 2021). "Moreover, in animal experiments, forced expression of NUDT21 promoted tumor growth and cell proliferation in gastric cancer cells, and depletion of NUDT21 restrained lung metastasis of gastric cancer cells." (PMID 34660260, 2021). "Therefore, we provided evidence that NUDT21 played an important oncogenic role in human gastric cancer." (PMID 34660260, 2021). "Therefore, NUDT21 stimulated cell proliferation and metastasis in gastric cancer cells through specific regulation of SGPP2." (PMID 34660260, 2021). "shRNA mediated depletion of NUDT21 dramatically decreased cell viability, cell colony formation, cell proliferation, cell migration and invasion in gastric cancer cells as determined by MTT assay, cell colony formation assay, EdU assay, cell migration assay and cell invasion assay respectively." (PMID 34660260, 2021). "Gastric cancer tissues (especially with tumor metastasis) expressed high level of NUDT21." (PMID 34660260, 2021). "Therefore, the expression levels of NUDT21 were higher in human gastric cancer tissues/cells compared with normal gastric tissues/cells." (PMID 34660260, 2021). "Moreover, forced expression of NUDT21 in gastric cancer cells promoted tumor growth and cell proliferation in xenograft nude mice, and depletion of NUDT21 in gastric cancer cells restrained lung metastasis in vivo." (PMID 34660260, 2021). "Moreover, these 70 gastric cancer patients were followed up for more than 5 years, and the correlation between NUDT21 expression and patient overall survival (OS) rates was analyzed through Kaplan-Meier analysis." (PMID 34660260, 2021). "In summary, we have demonstrated the oncogenic role of NUDT21 in human gastric cancer cells." (PMID 34660260, 2021). "Depletion of NUDT21 decreased both cell proliferation and metastasis in gastric cancer cells." (PMID 34660260, 2021). "Moreover, the mRNA levels of NUDT21 were dramatically higher in gastric cancer tissues from patients with distant metastasis compared with gastric cancer tissues from patients without distant metastasis." (PMID 34660260, 2021). "Therefore, NUDT21 promoted gastric cancer cell proliferation, tumor growth and tumor metastasis in vivo." (PMID 34660260, 2021). "Therefore, NUDT21 stimulated cell proliferation, migration and invasion in human gastric cancer cells." (PMID 34660260, 2021). "Moreover, the protein levels of NUDT21 in gastric cancer cells AGS, BGC-823, SGC-7901, HGC-27, MKN-28 were also much higher compared with normal gastric cell line GES-1 as determined by western blot." (PMID 34660260, 2021).